CCR1 (C-C motif chemokine receptor 1)
Diseases named in the same sentence as CCR1 in open-access papers (continued):
Sharing a sentence is not in itself a finding about the gene and the disease.
autoimmune myocarditis (1 paper, 2021). Autoimmune myocarditis is an autoimmune disease that affects the heart. "Elevated levels of CCR1, CCR2, and CCR5 expression in the heart of A/J mice that were immunized with cardiac troponin I to develop autoimmune myocarditis were previously reported." (PMID 34944410, 2021).
B cell lymphoma (1 paper, 2021). "Each chemokine was tested for its ability to chemoattract L1.2 mouse B cell lymphoma cells expressing the cognate mouse receptors Ccr6, Ccr7, and Ccr1, respectively, in the presence of increasing doses of DOPS or DOPC liposomes." (PMID 34038417, 2021).
bone tumor (1 paper, 2017). "Inactivation of CCR1 suppresses not only cancer cells but also cells in the bone tumor microenvironment reducing the overall osteolytic tumor burden." (PMID 28300755, 2017).
brain hemorrhage (1 paper, 2022). "For example, CCR1 expressed by microglia after brain hemorrhage can be activated through the CCR1/tetratricopeptide repeat 1 (TPR1)/extracellular signal-regulated kinase 1/2 (ERK1/2) signaling pathway, thereby promoting the development of neuroinflammation." (PMID 36711145, 2022).
Cachexia (1 paper, 2022). Severe weight loss, wasting of muscle, loss of appetite, and general debility related to a chronic disease. "These CCR1+ macrophages expressed cachexia mediators Tnf, Il1b, and Il6." (PMID 35031523, 2022).
cerebral aneurysms (1 paper, 2025). "Non-selective inhibitor of CCR1 and CCR2, capable of reducing BP, increasing blood flow, and reducing arterial wall thickness in SHR animals; In C57BL/6 mice, it was able to reduce the formation of cerebral aneurysms." (PMID 40859641, 2025).
cerebral malaria (1 paper, 2005). A sequestration of Plasmodium falciparum in the brain, which can cause coma and/or seizures. "In this study, the expressions of RANTES and its corresponding receptors CCR1, CCR3 and CCR 5 were up-regulated in the brain during P. yoelii 17XL infection, further implicating these molecules in the pathogenesis of rodent cerebral malaria." (PMID 16359553, 2005).
cholangiocarcinoma (1 paper, 2017). A carcinoma that arises from the intrahepatic biliary tree (intrahepatic cholangiocarcinoma) or from the junction, or adjacent to the junction, of the right and left hepatic ducts (hilar cholangiocarcinoma). "In our present study, MSCs under inflammatory condition exhibited higher expression levels of CCL5 than control MSCs cells, and co-culture of cholangiocarcinoma cells with MSC(TI)-CM induced upregulation of CCR1, CCR3 and CCR5 expression." (PMID 29088737, 2017).
co-infection (1 paper, 2015). "In addition, co-infection significantly regulated the mRNA expression of several chemokine and chemokine receptor genes, including CCL3 (1.62-fold), CX3CL1 (1.7-fold), CXCL16 (0.56-fold), CCR1 (2.23-fold), and CXCR4 (1.55-fold)." (PMID 25906258, 2015).
Crohn disease (1 paper, 2012). A gastrointestinal disorder characterized by chronic inflammation involving all layers of the intestinal wall, noncaseating granulomas affecting the intestinal wall and regional lymph nodes, and transmural fibrosis. "More recently, promising but preliminary results were reported for the CCR1 inhibitor CCX354-C in RA patients as well as the CCR9 inhibitor CCX282 in Crohn’s disease and inflammatory bowel disease." (PMID 22912856, 2012).
disc degeneration (1 paper, 2023). "In support of the role of Ccr1 in promoting macrophage infiltration during IVD degeneration, blocking Ccr1/2 in a rabbit annular puncture model decreased disc degeneration, limited inflammation, and blocked macrophage migration in vitro." (PMID 36674887, 2023).
endotoxemia (1 paper, 2009). "We have previously reported that primary diaphragmatic myotubes also demonstrate significant upregulation of CCR1 but not CCR5 during proinflammatory cytokine stimulation in vitro, which is in keeping with the greater upregulation of CCR1 during endotoxemia shown in the present study." (PMID 19421418, 2009).
Gaucher disease (1 paper, 2024). Gaucher disease (GD) is a lysosomal storage disorder encompassing three main forms (types 1, 2 and 3), a fetal form and a variant with cardiac involvement (Gaucher disease - ophthalmoplegia - cardiovascular calcification or Gaucher-like disease). "Moreover, given that studies are increasingly recognizing the role of immune dysregulation and inflammation driven by chemokines such as CCL18 in the pathogenesis of Gaucher disease, CCR1 modulation could also be relevant for the Gaucher patients developing PD." (PMID 38673922, 2024).
gingivitis (1 paper, 2020). A disorder involving inflammation of the gums; may affect surrounding and supporting structures of the teeth. "CCR1 has an important role in the occurrence of chronic inflammation of gingivitis." (PMID 34026747, 2020).
glaucoma (1 paper, 2009). Increased pressure in the eyeball due to obstruction of the outflow of aqueous humor. "Major membrane receptors affected in glaucoma included ICAM1 (up-regulated), PDGF-Rα and CCR1 (down-regulated)." (PMID 19426536, 2009).
glomerular disease (1 paper, 2025). "Rather than global CCL5 inhibition, selective CCR1/CCR5 antagonism in macrophages may preserve the podocyte-protective effects of CCL5 while mitigating its proinflammatory activity, offering a more refined therapeutic strategy for glomerular disease." (PMID 40986444, 2025).
gout (1 paper, 2023). A condition characterized by painful swelling of the joints, which is caused by deposition of urate crystals. "Furthermore, the CCL5 ligand and its receptor, CCR1, acted as major signals from cytotoxic CD8+ TCs to CMs primarily during gout flares compared with during remission." (PMID 38063198, 2023).
Graves disease (1 paper, 2016). Graves' disease is an autoimmune disorder that leads to overactivity of the thyroid gland (hyperthyroidism).It is caused by an abnormal immune system response that causes the thyroid gland to produce too much thyroid hormones. "They concluded that RANTES (regulated on activation, normal T cells expressed and secreted) in interaction with its receptors (CCR1, CCR3, CCR4, and CCR5), mainly on the lymphocytes, may be involved in the maintenance of lymphocytic infiltration and the autoimmune responses in Graves' disease." (PMID 27872865, 2016).
Heat Stroke (1 paper, 2023). A condition caused by the failure of body to dissipate heat in an excessively hot environment or during PHYSICAL EXERTION in a hot environment. "In primary cultured astrocytes, scRNA-seq and qPCR showed upregulation of C6, CCL3, and CCR1 after heat stress but downregulation in heat stroke rats, while the transcriptional levels of CCL3 and CCR1 were downregulated in heat stroke rats." (PMID 37078089, 2023).
Hepatic steatosis (1 paper, 2015). Steatosis is a term used to denote lipid accumulation within hepatocytes. "Expression levels of C-C chemokine receptor 1 (CCR1) and chemokine (C-X-C motif) ligands 9, 10, 14 (CXCL9, CXCL10, and CXCL14) are increased in livers during HFD-induced hepatic steatosis." (PMID 25887406, 2015).
invasive breast carcinoma (1 paper, 2021). A carcinoma that infiltrates the breast parenchyma. "In our present study, we performed immunohistochemistry for CCL5 and its receptors, CCR1, 3 and 5, in 111 invasive breast carcinoma tissues." (PMID 33671956, 2021).
ischemia (1 paper, 2022). A hypoperfusion of the BLOOD through an organ or tissue caused by a PATHOLOGIC CONSTRICTION or obstruction of its BLOOD VESSELS, or an absence of BLOOD CIRCULATION. "Of note, CCR1 is an important receptor that is implicated in neutrophil trafficking to post-ischemic tissues and ischemia is an important co-morbidity associated with impaired healing in diabetic wound." (PMID 35112667, 2022).
Kawasaki disease (1 paper, 2021). A rare inflammatory disease characterized by an acute febrile, systemic, self-limiting, medium-vessel vasculitis primarily affecting children. "Our study shows that we can distinguish normal samples from Kawasaki disease samples based on the infiltration of immune cells, and that CXCL8, CCL5, CCR7, CXCR3, and CCR1 may play important roles in the development of Kawasaki disease." (PMID 33188570, 2021).
lymph node metastasis (1 paper, 2021). "CCL5 immunoreactivity was not correlated with any clinicopathological factors in the CCR1-positive group (n = 21), while it was negatively correlated with pathological T factor (pT) (p = 0.037) and lymph node metastasis (p = 0.024) in the CCR5-positive group (n = 45)." (PMID 33671956, 2021). "In the CCR1-negative/CCR3-positive/CCR5-negative group, CCL5 immunoreactivity was significantly correlated with the pT, histological grade, Ki67 LI and MVD and tended to be correlated with lymph node metastasis while negatively correlated with the ER and PR." (PMID 33671956, 2021).
malaria (1 paper, 2005). Malaria is a serious and sometimes fatal disease caused by a parasite that commonly infects a certain type of mosquito which feeds on humans. "The upregulation of RANTES, CCR1, CCR3, and CCR5 mRNA, and RANTES protein mediate inflammation and cellular degradation in the cerebellum during P. yoelii 17XL malaria." (PMID 16359553, 2005). "The hypothesis of this study is that RANTES and its corresponding receptors (CCR1, CCR3 and CCR5) modulate malaria immunopathogenesis." (PMID 16359553, 2005).
myelofibrosis (1 paper, 2022). A partial or complete replacement of the bone marrow stroma by fibrous tissue. "However, the known receptors for CXCL4, CXCR3, and CCR1 are not expressed on bone marrow MSCs, suggesting that CXCL4 acts in an indirect fashion to induce myelofibrosis." (PMID 35439167, 2022).
neuropathic pain (1 paper, 2022). Chronic pain caused by damage to nerve fibers. "In light of our research, we propose that CCL2/7/8/CCR1 and CCL7/8/CCR3 signaling are important elements in the modulation of neuropathic pain." (PMID 36611891, 2022).
non-small cell lung carcinoma (1 paper, 2020). A group of at least three distinct histological types of lung cancer, including non-small cell squamous cell carcinoma, adenocarcinoma, and large cell carcinoma. "It was also implicated in the suppression, migration and invasion of non-small-cell lung cancer cells via targeting CCR1 as well as other molecular functions, but it was not considered as a suitable reference gene." (PMID 32005151, 2020).
oral squamous cell carcinoma (1 paper, 2017). "The expression of CCL3 and its receptors CCR1 and CCR5 was demonstrated in oral squamous cell carcinoma (OSCC), but their role was not defined." (PMID 28881626, 2017).
osteoarthritis (1 paper, 2024). A noninflammatory degenerative joint disease occurring chiefly in older persons, characterized by degeneration of the articular cartilage, hypertrophy of bone at the margins and changes in the synovial membrane. "In vivo, BX471 protected cartilage and reduced osteophyte formation, suggesting the therapeutic potential of CCR1 inhibition in experimental osteoarthritis." (PMID 38831316, 2024). "Our data clearly demonstrated the expression of CCR1 in chondrocytes and its upregulation under inflammatory stimuli in vitro and in a low-grade inflammatory microenvironment, such as osteoarthritis (OA)." (PMID 38831316, 2024).
peritonitis (1 paper, 2014). Inflammation of the peritoneum (tissue that lines the abdominal wall and covers most of the organs in the abdomen). "In order to explore the role of CCR1 in inflammation and pain, we generated CCR1−/− mice and confirmed a reduction in immune cell trafficking utilizing a 4 hr thioglycollate-induced peritonitis model." (PMID 25170619, 2014). "Studies with our CCR1−/− mice and small molecule CCR1 antagonists show reduced immune cell trafficking in a peritonitis model and reduced disease severity in CAIA." (PMID 25170619, 2014). "Consistent with previously published reports, we demonstrate that CCR1 deletion or antagonism with a small molecule restricts immune cell trafficking in a peritonitis model and reduces disease severity in a model of collagen antibody-induced arthritis (CAIA)." (PMID 25170619, 2014).
Pneumovirus Infections (1 paper, 2005). Infections with viruses of the genus PNEUMOVIRUS, family PARAMYXOVIRIDAE. "Finally, a recent study examined the effects of inhibiting the CC chemokine receptor, CCR1, during live-virus exposure in mice and showed that mortality during pneumovirus infection was decreased." (PMID 15921526, 2005).
prion disease (1 paper, 2020). A transmissible disease that is caused by a protein that is able to induce abnormal folding of normal cellular proteins, leading to characteristic spongiform brain changes, which are associated with neuronal loss without an inflammatory response. "To contrast, prion infected-CCR1 KO mice (lacking the RANTES receptor) showed a worsened prion disease course and a lower survival rate with respect to infected WT mice." (PMID 33092220, 2020).
pulmonary arterial hypertension (1 paper, 2013). Pulmonary arterial hypertension (PAH) is a group of diseases characterized by mean pulmonary artery pressure >20 mmHg and elevated pulmonary arterial resistance leading to right heart failure. "In addition, gene expression of CCR1 was shown to be upregulated in PBMCs derived from patients with lcSSc and pulmonary arterial hypertension." (PMID 23845159, 2013).
renal failure (1 paper, 2012). "Second, Ccr1 deficiency was associated with markedly decreased destructive inflammatory changes and tissue injury in the kidney; this was accompanied by less severe kidney failure in Ccr1−/− mice, which is a major determinant of survival in the model." (PMID 22916017, 2012).
retinal degeneration (1 paper, 2023). Degeneration of the retina. "Further experiments are required to assess the effect of CCR1 inhibition in rd10 and senescent mice and validate the protective effect of CCR1 antagonist during retinal degeneration." (PMID 37903056, 2023). "Next, we examined whether CCR1 is also upregulated in other models of retinal degeneration." (PMID 37903056, 2023). "Based on our finding that CCR1 expression is upregulated in the retina in: (i) photic-injured mice, (ii) rd10 mice in parallel with the onset of retinal degeneration, and (iii) senescent mice, we hypothesized that inhibiting this receptor may slow the rate of photoreceptor loss." (PMID 37903056, 2023).
retinal pigmentosa (1 paper, 2017). "The suppression of both CCR3 and CCR1 signaling may have the stronger potential than the suppression of selective CCR3 signaling against the photoreceptor degeneration which is observed in dry AMD and retinal pigmentosa." (PMID 28458639, 2017).
schistosomiasis (1 paper, 2012). An infectious disease caused by parasitic trematodes of the genus Schistosoma that colonize human blood vessels and release eggs that can cause granulomatous reactions leading to acute (swimmer's itch or acute schistosomiasis syndrome) or chronic disease. "There were 3 chemokine receptors in cluster 2 including CCR1, CXCR4 and CXCR7, which showed sustained up-regulation during both the acute and chronic stages of schistosomiasis mice." (PMID 22905138, 2012). "Cluster analysis showed that CCR1 was highly correlated with type I and III collagen, suggesting that it might also promote fibrosis in schistosomiasis." (PMID 22905138, 2012).
serous ovarian cancer (1 paper, 2012). "In the regulatory networks of CCR1 in adipose tissue and cyclins in serous ovarian cancer, we observed that upstream regulators of CCR1 and cyclins not only regulated CCR1 and cyclins but also regulated each other." (PMID 22443377, 2012).
sexually transmitted infections (1 paper, 2025). "This may include a complete blood count, cancer antigen (CA-125), chemokine receptor (CCR1), urinalysis, and tests for sexually transmitted infections." (PMID 40003570, 2025).
Shock (1 paper, 2025). The state in which profound and widespread reduction of effective tissue perfusion leads first to reversible, and then if prolonged, to irreversible cellular injury. "This implies that the release of endogenous CCR1 agonists during hemorrhagic shock and resuscitation contributes to increased systemic fluid requirements and provides a rationale for the beneficial effects of BX471." (PMID 40427068, 2025). "In addition, while this study was designed to provide initial evidence for therapeutic efficacy of CCR1 blockade after hemorrhagic shock, it is unable to address the mechanisms by which these effects occurred." (PMID 40427068, 2025).
silicosis (1 paper, 2025). Silicosis is a respiratory disease caused by breathing in (inhaling) silica dust. "Collectively, the current study demonstrates that HHT shows significant potential as a therapeutic agent for silicosis by targeting CCR1 and the PI3K/AKT/mTOR signaling pathway, highlighting it as a promising candidate for clinical translation for silicosis treatment." (PMID 40396273, 2025).
skin inflammation (1 paper, 2024). "Chi3l3 and Ccr1 play important roles in regulating skin inflammation, and the Fcεr1a gene is crucial in controlling immune responses mediated by IgE43–45." (PMID 38834629, 2024).
tongue tumours (1 paper, 2017). "CCL3-/- and CCR5-/- mice presented reduced incidence of tongue tumours compared to wild-type (WT) and CCR1-/- mice." (PMID 28881626, 2017).
Trypanosoma cruzi infection (1 paper, 2020). "However, a Brazilian genetic polymorphism study of CCR1, CCR5, and their ligands CCL2 and CCL5, respectively, found CCL5-CCR1 to be the target for immune-stimulation from Trypanosoma cruzi infection." (PMID 32257106, 2020).
Ureteral obstruction (1 paper, 2016). Obstruction of the flow of urine through the ureter. "Even though CCR1 and CCR5 share the same chemokine ligands, studies with unilateral ureteral obstruction and renal ischemia-reperfusion injury models have shown that CCR1 but not CCR5 is essential for T cells, macrophages, and neutrophils infiltration in the tubulointerstitial region of the kidney." (PMID 27403037, 2016).
uveitis (1 paper, 2025). An inflammatory process affecting a part of or the entire uvea. "For instance, metaDEGs of the uveitis only group comprise genes that are involved in the innate immune response, such as chemokine receptors (CX3CR1, CCR1, and CCR2), and Toll-like receptors (TLR4, TLR7, TLR8, and the TLR4 homologous receptor, CD180)." (PMID 40270958, 2025).
vasculitis (1 paper, 2021). "Moreover, CCR1 is prognostic factor in palliative inductive therapy for vasculitis." (PMID 33188570, 2021).